H4C6 (H4 clustered histone 6)
Description:
Core component of nucleosome. Nucleosomes wrap and compact DNA into chromatin, limiting DNA accessibility to the cellular machineries which require DNA as a template. Histones thereby play a central role in transcription regulation, DNA repair, DNA replication and chromosomal stability. DNA accessibility is regulated via a complex set of post-translational modifications of histones, also called histone code, and nucleosome remodeling.
Synonyms: H4/C; H4FC; HIST1H4F; H4
Target class: Other nuclear protein
Gene: Protein-coding gene on chromosome 6 (26,240,393 to 26,240,793, forward strand). Ensembl gene ENSG00000274618.
Subcellular location: Nucleus; Chromosome
Pathways (Reactome):
Gene expression (Transcription): B-WICH complex positively regulates rRNA expression; DNA methylation; ERCC6 (CSB) and EHMT2 (G9a) positively regulate rRNA expression; MLL4 and MLL3 complexes regulate expression of PPARG target genes in adipogenesis and hepatic steatosis; NoRC negatively regulates rRNA expression; PRC2 methylates histones and DNA; RNA Polymerase I Promoter Escape; RNA Polymerase I Promoter Opening; RUNX1 regulates genes involved in megakaryocyte differentiation and platelet function; RUNX1 regulates transcription of genes involved in differentiation of HSCs; Regulation of endogenous retroelements by KRAB-ZFP proteins; Regulation of endogenous retroelements by Piwi-interacting RNAs (piRNAs); Regulation of endogenous retroelements by the Human Silencing Hub (HUSH) complex; SIRT1 negatively regulates rRNA expression; Transcriptional regulation by small RNAs
Chromatin organization: CHD1 and CHD2 subfamily; CHD6, CHD7, CHD8, CHD9 subfamily; ChAHP complex assembly; HATs acetylate histones; HDACs deacetylate histones; HDMs demethylate histones; Interaction of NuRD complexes with transcription factors; NuRD complex assembly; PKMTs methylate histone lysines; RMTs methylate histone arginines
DNA Repair: Cleavage of the damaged purine; Cleavage of the damaged pyrimidine; Nonhomologous End-Joining (NHEJ); Processing of DNA double-strand break ends; Recognition and association of DNA glycosylase with site containing an affected purine; Recognition and association of DNA glycosylase with site containing an affected pyrimidine; Recruitment and ATM-mediated phosphorylation of repair and signaling proteins at DNA double strand breaks
Cell Cycle: Condensation of Prophase Chromosomes; Deposition of new CENPA-containing nucleosomes at the centromere; G2/M DNA damage checkpoint; Inhibition of DNA recombination at telomere; Packaging Of Telomere Ends
Developmental Biology: Activation of anterior HOX genes in hindbrain development during early embryogenesis; Chromatin modifications during the maternal to zygotic transition (MZT); Replacement of protamines by nucleosomes in the male pronucleus
and 20 more pathways
Gene Ontology:
Molecular function: protein binding; RNA binding; structural constituent of chromatin; DNA binding; protein heterodimerization activity
Biological process: negative regulation of megakaryocyte differentiation; nucleosome assembly; chromatin organization; protein localization to CENP-A containing chromatin; telomere organization
Cellular component: CENP-A containing nucleosome; chromosome, telomeric region; extracellular exosome; membrane; nucleoplasm; nucleosome; nucleus; protein-containing complex; extracellular region; chromosome
Genetic constraint (gnomAD): Loss-of-function variants: 8 observed, 5.87 expected, observed/expected ratio (o/e) 1.36, 90% interval 0.77 to 1.91. That is too few expected variants to judge how well the gene tolerates losing a copy. Missense variants: 230 observed, 155.68 expected, observed/expected ratio (o/e) 1.48, 90% interval 1.33 to 1.65. Synonymous variants: 124 observed, 61 expected, observed/expected ratio (o/e) 2.03.
Homologues: Orthologues: chimpanzee H4C6 (100% identical), mouse H4c17 (100% identical), tropical clawed frog h4c3 (100% identical). Paralogues in human: H4C1 (100% identical), H4C11 (100% identical), H4C12 (100% identical), H4C13 (100% identical), H4C14 (100% identical), H4C15 (100% identical), H4C16 (100% identical), H4C2 (100% identical), H4C3 (100% identical), H4C4 (100% identical), H4C5 (100% identical), H4C8 (100% identical), and 2 more.
Diseases named in the same sentence as H4C6 in open-access papers:
H4C6 is named in the same sentence as 2 diseases in open-access papers, as found by Europe PMC text mining. Sharing a sentence is not in itself a finding about the gene and the disease. The quoted sentences say what the papers report.
cancer (2 papers, 2023 to 2025). A tumor composed of atypical neoplastic, often pleomorphic cells that invade other tissues. "For instance, we use it to identify novel cancer-related genes, i.e. PRDM11, C9orf72, MINDY3, and H4C6, that could have an important role in the studied cancer types." (PMID 37084262, 2023). "The protein network of unique cancer cell genes in the “cancer cells_vs_all-PDAC” group exhibited top 10 hub genes, including H4C6 (HIST1H4A or HIST1H4C), MYC, H3C12 (HIST1H3A or HIST1H3D), DDX21, USP7, RFC4, APEX1, CDK9, H2BC9 (HIST1H2BH), and NOP2." (PMID 40906153, 2025). "Additionally, the TISCH2 indicated that all the hub-genes of cancer cells were upregulated in malignant cells, especially GAPDH, RHOA, TPI1, H4C6, DDX21, and APEX1, which showed considerably high expression levels in malignant cells." (PMID 40906153, 2025).
head/neck tumors (1 paper, 2025). "H4C6, also known as HIST1H4F, is considered as a pan-oncogene and has been shown to be highly methylated in a variety of cancerous tissues including head/neck tumors but hypomethylated in benign tissues." (PMID 40618071, 2025).